ATF4 (activating transcription factor 4)
Diseases named in the same sentence as ATF4 in open-access papers (continued):
Sharing a sentence is not in itself a finding about the gene and the disease.
cardiovascular disease (9 papers, 2012 to 2026). "ATF4 has been reported to be associated with cardiovascular disease." (PMID 38913045, 2024). "Recently, ATF4 has become an increasingly prominent topic of investigations on cardiovascular diseases, and accumulating evidence has unveiled that the role of ATF4 in cardiovascular disorders is also dual-sided." (PMID 41561820, 2026). "This review provides an insight into the dichotomous roles and corresponding mechanisms of ATF4 in different kinds of cardiovascular disorders." (PMID 41561820, 2026). "This table lists the cardiovascular conditions, ATF4 expression patterns, downstream targets, functional roles, model systems and references, offering a comprehensive overview of the roles and mechanisms of ATF4 in cardiovascular diseases." (PMID 41561820, 2026). "A comprehensive understanding of the dual effects and mechanisms of ATF4 in cardiovascular disorders holds promise for the development of personalized prevention and therapeutic avenues." (PMID 41561820, 2026). "For instance, by cooperating with the traditional Chinese medicine teams, we can screen the traditional drug components that can regulate ATF4 to protect against cardiovascular diseases." (PMID 41561820, 2026). "This contradictory nature positions ATF4 as a pivotal molecule for understanding cardiovascular disease mechanisms and developing personalized targeted therapies." (PMID 41561820, 2026). "EIF3A was found to directly bind with 5′ UTR of ATF4, a critical antagonizing factor of oxidative stress in cardiovascular disease, and regulated the protein expression of ATF4 in a m6A dependent-manner." (PMID 36743697, 2023). "For ATF4, it has been verified to play an important role in cardiovascular diseases using reverse transcription/real-time polymerase chain reaction and western blotting." (PMID 22923290, 2012). "In summary, as the core regulator of cellular stress, ATF4 plays essential context-specific roles in cardiovascular diseases, and targeting ATF4 may represent novel therapeutic approaches for cardiovascular pathologies." (PMID 41561820, 2026). "Besides, the mechanism of functional transformation of ATF4 during different stages of cardiovascular diseases also remains to be elucidated." (PMID 41561820, 2026). "This review provides in-depth insights into the functional paradoxes and clinical translational potential of ATF4 in cardiovascular pathologies, which is conducive to promoting interdisciplinary cooperation to address the complexity of cardiovascular disease treatment." (PMID 41561820, 2026). "Hence, this review is intended for readers across disciplines who are interested in ATF4, cellular stress response and cardiovascular diseases." (PMID 41561820, 2026). "The roles and mechanisms of ATF4 in cardiovascular diseases." (PMID 41561820, 2026). "Therefore, based on the cutting-edge evidence, this review aims to provide an overview of the conflicting roles of ATF4 in the pathogenesis of various cardiovascular diseases and also highlights the potential regulatory mechanisms." (PMID 41561820, 2026). "Despite these promising results of investigations for cardiovascular disease, the role of PERK/eIF2α/ATF4 inhibition in VSMC function during AAA development remains to be fully defined." (PMID 39846252, 2025). "We found that four of the predicted disease genes, namely, ATF4, MBNL1, NCKAP1 and CXCL14, have been reported to be related to cardiovascular diseases." (PMID 22923290, 2012). "Taken together, this study supports that the ATF4/PHGDH axis may represent a promising target for delaying cellular senescence and age-related cardiovascular diseases." (PMID 41561820, 2026).
kidney disease (4 papers, 2022 to 2025). "Thus, the functions of ATF4 appear to be complex under the condition of kidney diseases." (PMID 41479926, 2025). "Of note, despite being in the set of kidney disease, we indicated a novel ATF4 regulatory mechanism, which is independent of the canonical signaling from either the unfolded protein response or the integrated stress response." (PMID 41479926, 2025).
mitochondrial disease (4 papers, 2015 to 2021). "ATF4 has been implicated in the mitochondrial stress response in cellular and mouse models of mitochondrial disease." (PMID 34285383, 2021). "ATF4 is known to activate serine biosynthesis, and increased serine has been observed in a number of mitochondrial disease settings, albeit with less consistency." (PMID 27307216, 2016). "We note that our observation of ATF4 activation and alterations in serine metabolism and transsulfuration is richly supported by recent studies of mitochondrial disease." (PMID 27307216, 2016). "Future efforts to decipher the mechanism and physiological consequences of cold-induced ATF4 signaling in BAT may therefore help elucidate the role of the ISR in mitochondrial disease." (PMID 31042465, 2019).
adenocarcinoma (2 papers, 2018 to 2020). A common cancer characterized by the presence of malignant glandular cells. "The correlations between eIF2α and ATF4 were insignificant in the normal tissue of adenocarcinoma." (PMID 30305853, 2018). "The protein levels of ATF4, eIF2α, and IRF1 were correlated with that of PDL1 in all the tissues except the normal one of adenocarcinoma." (PMID 30305853, 2018).
bacterial infection (2 papers, 2016 to 2025). "The roles of IRE-1, PERK, and ATF4 in viral and some bacterial infections are well characterized." (PMID 27499755, 2016).
immune dysfunction (2 papers, 2025). "ELF3 and ATF4 were identified as key regulators linking butyrate metabolism to PD-1 expression, providing a molecular bridge between microbiome and immune dysfunction." (PMID 41438381, 2025).
infectious disease (2 papers, 2018 to 2021). A disorder directly resulting from the presence and activity of a microbial, viral, or parasitic agent in humans. "Taken together, these observations are consistent with our results that ATF4 was involved in host immune response to an infectious disease." (PMID 30647960, 2018). "Future efforts are needed to explore the role of ATF4 in immune response of human, which may provide us a potential therapeutic target for the infectious diseases." (PMID 34804026, 2021).
myopathy (2 papers, 2022 to 2023). A disease of the muscle in which the muscle fibers do not function properly. "ATF4‐mediated upregulation of asparagine synthetase (ASNS) was found at the early stage of myopathy and increased markedly at later stages (1.7‐, 9‐, and 9‐fold at 50, 100, and 200 days, respectively)." (PMID 37222423, 2023). "Though problems with antibodies may explain this, the dependence on ATF4 of myopathy adaptation has not been determined." (PMID 35531957, 2022).
animal disease (1 paper, 2017). "This is also indicated by the fact that most, if not all, published works that have studied the consequences of direct modulation of ATF4 in animal disease models indicate that restriction of the excessive protein production can significantly diminish retinal and neurodegenerative disorders." (PMID 29326555, 2017).
digestive diseases (1 paper, 2025). "This bidirectional regulation reflects a tightly controlled feedback system, positioning ATF4–lncRNA interactions as potential targets for therapeutic intervention in digestive diseases." (PMID 40777108, 2025). "In digestive system diseases, HCC cell lines under glucose-deprivation conditions have demonstrated ATF4-dependent upregulation of lncRNAs such as GIMA and LINC01564, promoting autophagy and serine biosynthesis, respectively." (PMID 40777108, 2025).
hematologic malignancies (1 paper, 2022). "Thus, ATF4 plays a central role in the pathogenesis of a number of hematologic malignancies." (PMID 36348393, 2022). "Given that ATF4 regulates the expression of NOXA, a known protein antagonist of MCL1, these findings further support the potential of modulating the ISR to therapeutically induce mitochondrial apoptosis in hematologic malignancies." (PMID 36348393, 2022). "Additionally, pyrvinium pamoate stimulated the increased transcription of a number of pro-apoptotic ATF4 target genes, including NOXA, PUMA and CHOP further supporting the potential for modulation of the ISR as a therapeutic strategy for hematologic malignancies." (PMID 36348393, 2022).
psychiatric disorder (1 paper, 2023). A disorder characterized by behavioral and/or psychological abnormalities, often accompanied by physical symptoms. "In addition, ATF4 has been shown to interact with Disrupted-in-Schizophrenia 1, a risk factor for major mental illnesses and regulate dopaminergic signaling by repressing transcription of phosphodiesterase 4D, a gene involved in psychiatric disorders." (PMID 37906604, 2023).
retinopathy (1 paper, 2021). "An earlier study showed that genetic deletion of ATF4 reduced the expression of VEGF and resulted in attenuating the degree of angiogenesis in the oxygen-induced-retinopathy (OIR) model that was used to study retinal pathological angiogenesis." (PMID 34445595, 2021).
skeletal dysplasia (1 paper, 2017). Any Mendelian diseases that affects growth and development of the skeleton. "In MCDS mice expressing the Col10a1.pN617K mutation, CBZ reduced the MCDS-associated expansion of the growth plate hypertrophic zone, attenuated enhanced expression of ER stress markers such as Bip and Atf4, increased bone growth, and reduced skeletal dysplasia." (PMID 28920921, 2017).
ATF4 also shares sentences with these, for which no sentence is quoted: liver (4 papers); cocaine addiction (3); non-alcoholic fatty liver disease (3); prostate adenocarcinoma (3); skeletal diseases (3); Anxiety (2); aortic valve disease (2); Arthritis (2); cataract (2); cholangiocarcinoma (2); chronic myelogenous leukemia (2); dilated cardiomyopathy (2); metabolic syndrome (2); Parkinson’s (2); respiratory diseases (2); Type 1 diabetes (2); acute myocardial infarction (1); acute promyelocytic leukemia (1); adenoid cystic carcinoma (1); alcoholic hepatitis (1); allergic contact dermatitis (1); amyloidosis (1); anaplastic astrocytoma (1); Anorexia (1); aortic stenosis (1); Arrhythmia (1); Autoimmunity (1); B-cell acute lymphoblastic leukemia (1); brain cancer (1); bronchiolitis obliterans syndrome (1).
A further 57 diseases each share a sentence with ATF4 in 1 paper.